FASLG (Fas ligand)
Diseases named in the same sentence as FASLG in open-access papers (continued):
Sharing a sentence is not in itself a finding about the gene and the disease.
tumor (continued). "CD8 + T cells can differentiate into effector cytotoxic T lymphocytes (CTLs), which have two main ways to kill tumor cells: granular exocytosis and Fas ligand (FasL)-mediated apoptosis induction." (PMID 35397536, 2022). "EVs secreted by tumor cells can carry immunosuppressive molecules including PD-L1, Fas ligand (Fas-L), TGF-β and prostaglandin E2 to the surrounding immune cells and contribute to the occurrence and development of tumors." (PMID 35958549, 2022). "The Fas ligand (FasL) and Apo2 ligand (Apo2L) appear to be more restricted to T lymphocyte-derived exosomes and exosomes from certain tumor cells." (PMID 35269412, 2022). "VEGFA has also been reported to upregulate the expression of Fas ligand (FasL/CD95L) of the tumor vasculature, which specifically induces apoptosis of CTLs but not Tregs." (PMID 35577211, 2022). "CTLs recognize MHC-I molecules expressed by tumor cells and specifically kill tumor cells through Granule exocytosis and Fas ligand (Fas-L)-mediated apoptosis induction." (PMID 36532071, 2022). "Tumor cells expressing Fas ligand (FasL) are involved in counterattacks to eliminate tumor-infiltrating lymphocytes." (PMID 36387244, 2022). "They induce tumor cell apoptosis by expressing death ligands, mainly Fas ligand (FasL) and TNF-related apoptosis-inducing ligand (TRAIL)." (PMID 35864520, 2022). "MDSCs within the tumor microenvironment present high levels of Fas-ligand (FasL) to trigger apoptosis of tumor-infiltrating lymphocytes (TILs)." (PMID 36362050, 2022). "The Fas ligand/Fas receptor system has a complex role in the tumor microenvironment, with cytotoxic T cells expressing Fas ligand to induce apoptosis in tumor cells and tumor cells upregulating Fas ligand to attack infiltrating lymphocytes." (PMID 36077825, 2022). "In one of the datasets, the expression of FASLG was also significantly higher in the controls compared to the tumor tissue." (PMID 36359256, 2022). "The IL-8 receptors CXCR1/2 are also specifically overexpressed in BCSCs compared with bulk tumor cells, and these cells are resistant to Fas ligand-induced apoptosis." (PMID 35216080, 2022). "This is mainly mediated by fibrinolytic enzymes in the CNS that cause shedding of Fas ligand from astrocyte membranes; the secreted Fas ligand triggers apoptosis of tumor cells." (PMID 36338717, 2022). "Tumor-derived EVs are high in immune regulatory molecules, including FasL (Fas ligand), TRAIL (TNF-related apoptosis-inducing ligand), and galactin-9, which can help cancer elude the immune system." (PMID 35159299, 2022). "T cell receptors can mediate antigen-dependent tumor cytotoxicity, directly induce cell death through membrane-bound Fas ligand, and inhibit tumor proliferation through secretion of IFN-gamma." (PMID 35027925, 2022). "NK cells have a broad spectrum of tumor-killing effects, which include ADCC, release of perforin and granzyme A/B, factor-associated suicide (Fas) and Fas ligand (FasL) interaction, and cytokine secretion." (PMID 36601109, 2022). "Human and mouse cancer models show that tumour endothelial cells display an increased expression of apoptotic Fas ligand in response to VEGF-A upregulation." (PMID 36045675, 2022). "The five TNFSF ligand transcripts were differentially expressed by all these subsets, with tumor-infiltrating germinal cells expressing the highest levels of TNF, LTA, TNFSF10 and LTB, and tumor-infiltrating plasma cells expressing the highest levels of FASLG." (PMID 35392082, 2022). "An increasing body of evidence suggests that resistance to ICI therapy is modulated by the Fas (CD95)–Fas ligand (FasL, CD178) interplay between tumor cells and immune cells." (PMID 33917866, 2021). "Activated NK cells release secretory lysosomes containing cytotoxic proteins (granzymes, perforin, etc.)to kill tumor cells, while cytotoxic T lymphocytes kill target cells by releasing granzymes or inducing Fas ligand-mediated apoptosis." (PMID 34830209, 2021).
tumor (continued). "Tumour-derived EVs (T-EVs) bearing Fas ligand (FasL) and TNF-related apoptosis-inducing ligand promote CTL apoptosis." (PMID 33401460, 2021). "Consecutively, CTLs are capable to kill tumor cells by the release of perforins and granzyme B or by a mechanism that involves Fas ligand (FasL, CD95L)-mediated apoptosis of target cells." (PMID 34135885, 2021). "NK cells are cytotoxic lymphocytes belonging to the innate immune system that can directly lyse target tumour cells via the secretion of perforin and granzymes or via Fas/Fas-ligand-induced apoptosis." (PMID 33923305, 2021). "CD8+ T-cells are an effector group of T-cells (T-killers), which play an important role in the anti-tumor immune response, as they can kill tumor cells by granule exocytosis and Fas ligand (FasL) (CD95)-mediated apoptosis." (PMID 33579033, 2021). "MSCs can alter the anti-tumor immune response and enable tumor progression through expression of immunomodulatory ligands, such as programmed death-ligand 1 (PD-L1), PD-L2, and Fas ligand." (PMID 33435170, 2021). "TAMs can also secrete MMP7 in hypoxic regions of tumors, which can cleave Fas-ligand from the neighboring cells, and form a soluble decoy, protecting tumor cells from Fas-ligand-mediated killing by T and NK cells." (PMID 33422072, 2021). "The second, somewhat slower mechanism of tumor cell killing relies on the signaling downstream of the Fas receptor upon the engagement of FasL (FASLG) that is displayed by the effector cell." (PMID 34834534, 2021). "Important immune barriers in the OC TME, including VEGF, Treg cells and tumor endothelial Fas ligand (FasL) can drive tumor angiogenesis and hinder the functions of antitumor T cells." (PMID 34572778, 2021). "MDSCs within the TME express high levels of Fas-ligand (FasL), capable of inducing apoptosis of tumor-infiltrating lymphocytes (TILs)." (PMID 34065010, 2021). "TAMs resident in the hypoxic areas of the tumour upregulate their expression of matrix metalloproteinase-7 protein, which cleaves Fas ligand from neighbouring cells rendering tumours less responsive to lysis by T-cells and natural killer (NK) cells." (PMID 33923305, 2021). "Cancer cells are exposed to Fas (CD95/APO-1) and the Fas ligand (FasL) mediated apoptosis pathway when engaged by tumor-killing lymphocytes." (PMID 34681277, 2021). "From a mechanistic point of view, iNKT cells, similarly to other cytotoxic populations, are known for inducing tumor cell death both by granzyme B/perforin production and by expression of Fas ligand (FasL) and TRAIL on their plasma membranes." (PMID 34535957, 2021). "The binding of B7-H6 to NKp30 activates NK cells and results in Fas ligand or granzyme-mediated apoptosis of target tumor cells." (PMID 34829829, 2021). "MMP-7 can also degrade the Fas ligand on the cell membrane, inhibit Fas-mediated apoptosis, and promote tumor growth." (PMID 34485109, 2021). "TNF receptors, such as TNF-related apoptosis-inducing ligand (TRAIL) and Fas ligand (FASL), can also kill tumor cells." (PMID 33707742, 2021). "CAFs induce depletion and dysfunction of tumor-specific T cells by antigen cross-presentation and cellular interactions mediated by Fas ligand (FASL) and programmed cell death 1 ligand 2 (PD-L2)." (PMID 34681633, 2021). "An increasing body of evidence, however, suggests that resistance to checkpoint inhibitor therapy is modulated by the Fas (CD95)–Fas ligand (FasL, CD178) interplay between tumor cells and immune cells." (PMID 33917866, 2021). "EVs secreted by tumor cells also harbor immunoinhibitory factors, such as Fas ligand and TNF-related apoptosis-inducing ligand, constraining the effect of antitumor immune cells and promoting their apoptosis." (PMID 34830787, 2021). "CD8 + T cells can directly induce cytolysis of target cells by releasing soluble cytotoxic molecules and Fas-Fas ligand (FasL) interaction, inducing skin depigmentation cytotoxic T-cell response." (PMID 34107850, 2021).
tumor (continued). "Regarding immune surveillance evasion, it should also be emphasized that tumor-secreted EVs can directly impair CD8+ T lymphocyte function by carrying the pro-apoptotic Fas Ligand (FasL) and the suppressive galectin-1 and -9, both in vitro and in vivo." (PMID 33670185, 2021). "Upregulation of VEGF, IL-10 and PGE2 at the tumour site cooperatively promotes Fas ligand expression on tumour endothelial to elicit apoptosis of CTLs, but not Tregs." (PMID 33401460, 2021). "We found that IDO1 expression was associated with clinical parameters, such as a presence of risk factors for HCC and tumor stage II and III, while the expression of FASLG in CCA patients was associated with the lymph node stage." (PMID 34069452, 2021). "NK cells are also able to induce apoptosis in tumor cells via TNF family molecules such as FAS ligand (FASL) and TNF-related apoptosis-inducing ligand (TRAIL)." (PMID 34885241, 2021). "Tumor-infiltrating MDSCs express high levels of Fas ligand (Fas-L) to induce apoptosis of CD8+ T cells by binding to the Fas receptor." (PMID 35004667, 2021). "mTAMs, which reside along the tumor margin and induce cancer cells to undergo apoptosis in a Fas ligand-dependent manner." (PMID 34797860, 2021). "Ultimately, CTLs induce tumor cell apoptosis through the release of perforin and granzyme B, or a combination of Fas ligand (FasL) with Fas." (PMID 34489957, 2021). "CD8 + T cell-derived exosomes with membrane expression of Fas ligand (FasL) can promote invasion and metastasis of Fas+ tumor cells through matrix metalloproteinase-9 (MMP-9)-mediated degradation of extracellular matrix proteins." (PMID 34266354, 2021). "These include the expression of endothelin B receptor and Fas ligand within the tumor endothelium, elevated levels of vascular endothelial growth factors (VEGF) which are commonly seen in HGSOC, and the presence of epigenetic silencing of Th1-type chemokines." (PMID 33927729, 2021). "Sun also found that Neutrophils isolated from healthy people promoted tumor cell apoptosis and inhibited tumor growth through Fas ligand/Fas pathway." (PMID 34123826, 2021). "For instance, tumour ECs are capable of boosting the level of Fas ligand (FasL) and thereby selectively kill effector CD8+ T cells in the presence of tumour-derived VEGF, prostaglandin E2 and IL-10 stimulation." (PMID 33917287, 2021). "CD8+ T cells, also known as cytotoxic T lymphocytes, can infiltrate into tumor tissue and kill malignant cells by releasing cytotoxic granules or by recognizing Fas ligand on the surface of target cells." (PMID 34204621, 2021). "Seven of 14 evaluable PanNEN G3 specimens showed FASLG immunoreactivity in the tumour cells while there was scattered immunoreactivity in immune cells." (PMID 32606315, 2020). "CD8+ T cells activated after recognizing TAA presented by MHC class I molecules on cancer cells can eliminate tumor cells via the action of perforin–granzyme or the Fas ligand (FasL)/TRAIL pathway." (PMID 31256327, 2020). "Tumor-derived exosomes were shown to mediate the conversion of CD4+ CD25− T cells into CD4+ CD25high FOXP3+ regulatory T cells with enhanced expression of Fas ligand, IL-10, TGF-β1, CTLA-4, granzyme B, and perforin." (PMID 32499786, 2020). "All FASLG immunoreactive tumour specimens exhibited an organoid structure, with diffuse cytoplasmic and a more evident peripheral membranous staining pattern." (PMID 32606315, 2020). "It belongs to the tumour necrosis factor (TNF) family, and binds to its receptor FAS on different cells and tissues, including tumour cells and immune cells, i.e. both FASLG and FAS can be expressed by the cytotoxic T lymphocytes." (PMID 32606315, 2020). "In our study the immunohistochemical results showed that 7/14 of the PanNEN G3 tumours expressed FASLG in the tumour cells." (PMID 32606315, 2020). "All were proteins expressed in higher concentrations in tumour samples than healthy controls, except for FASLG." (PMID 32606315, 2020).
tumor (continued). "MSCs express Fas ligand on their surface and stimulate the extrinsic pathway of apoptosis in tumor cells through Fas/Fas ligand connection." (PMID 32793565, 2020). "Tumour cells have adapted the expression of FASLG on their cell membranes to deactivate immune cells and hence, eliminate them from entering the tumour microenvironment." (PMID 32606315, 2020). "In our cohort, FASLG was inversely correlated to Ki-67 where patients with highly proliferative tumours had significantly lower blood concentrations of FASLG." (PMID 32606315, 2020). "This inhibitory ligand binds to its receptor, PD-1, suppressing T cell activation and promoting tumor escape and progression, while expression of Fas ligand (FasL) on PMN-MDSCs has been shown in pre-clinical studies to promote the apoptosis of TILs." (PMID 32244751, 2020). "In a chi-square test, well-differentiated tumours were significantly more immunoreactive for FASLG compared to poorly differentiated (p value = 0.018)." (PMID 32606315, 2020). "Fas ligand on NK cells interacts with the Fas receptor on tumor target cells, inducing the apoptosis of target cells." (PMID 32397120, 2020). "The VEGF signalling pathway can also provoke immune resistance as it induces Fas ligand, leading to cell death in tumour-infiltrating CD8+ T cells." (PMID 33023131, 2020). "In some studies it has been claimed that membrane bound FASLG induces apoptosis while soluble FASLG promotes tumour cell survival." (PMID 32606315, 2020). "CTLs initiate T-cell receptor (TCR)-mediated, antigen-dependent cytotoxicity against tumours, being capable of directly inducing cell death via membrane-bound FAS-ligand and inhibit tumour proliferation via IFN-γ secretion." (PMID 32157213, 2020). "Infiltrating CTLs uses two pathways to mediate tumor cytolysis, which is Fas ligand (FasL)—mediated apoptosis and granule exocytosis pathways." (PMID 32664247, 2020). "Correlation has been found between Fas ligand (FasL) expression on tumour cells and T cells undergoing apoptosis within the tumour microenvironment in subsets of OSCC patients." (PMID 32054041, 2020). "In hypoxic areas of tumors, the expression of matrix metalloproteinase proteins (MTX) cleave the Fas ligand from neighboring cells, making tumor cells less responsive to lysis by natural killer (NK) and T cells." (PMID 32244473, 2020). "FASLG in sera is reported to be increased in many cancers eluding to the mechanism of FASLG as a “counterattack” protein in different tumours." (PMID 32606315, 2020). "Both FAS and FASLG are important in cancer cell immunity as they have been seen to have both tumorigenic and tumour suppressive roles." (PMID 32606315, 2020). "Second, the tumor vasculature disables and kills CTLs by expressing various immunosuppressive molecules, such as PD-L1 and Fas ligand (FasL, also known as CD95L)." (PMID 32913278, 2020). "Some tumor cells express Fas ligand (FasL) molecule, which makes them capable of direct killing of immune cells that infiltrate tumors." (PMID 32610582, 2020). "Overexpression of FASLG by tumour cells has also been demonstrated to decrease the number of tumour infiltrating immune cells and increase apoptosis of immune cells." (PMID 32606315, 2020). "Positive FASLG immunoreactivity correlated to well-differentiated morphology.FASLG concentration in blood was significantly lower in patients with pancreatic NENs G3 compared to controls, and the expression in tumour tissue was variable." (PMID 32606315, 2020). "Granzyme B and perforin were examined as cytotoxic factors while FAS and Fas ligand (FasL) were examined as tumor apoptotic markers." (PMID 33042110, 2020). "In the presence of lenalidomide and pomalidomide, there is increased NK cell Fas Ligand (FasL) and granzyme B expression leading to tumor cell apoptosis." (PMID 32138182, 2020). "CD8+ T-cells are effector group of T-cells that can kill tumor cells by granule exocytosis and Fas ligand (FasL) (CD95)-mediated apoptosis." (PMID 32582698, 2020).
tumor (continued). "By packaging FASLG mRNA into exosomes, tumor cells disseminate overexpressed apoptotic signal to immune cells in the periphery." (PMID 33202950, 2020). "As a result, the target gene of miR-7e-5p, Fas ligand (FasL), was upregulated and activated the caspase signaling, which led to the apoptosis of M1 macrophages in tumor stroma." (PMID 33168041, 2020). "The higher Ki-67 index among the patients, the less concentrations of FASLG were seen in tumour samples, i.e. FASLG seems to be less present in patients with presumed poorer prognosis." (PMID 32606315, 2020). "Peripheral and tumor-associated NK cells in STAT3-targeted tumor-bearing mice, exhibit higher expression of the NK activation markers NKG2D, CD69, Fas ligand (FasL), granzyme B, perforin, and IFNγ, resulting in reduced tumor growth and enhanced survival." (PMID 31057536, 2019). "This suppression affects Fas ligand (FasL) expression in natural killer cells (NK cells), thus compromising their ability to kill FasL-sensitive tumor cells." (PMID 30837326, 2019). "Thirdly, the expression of Fas ligand (FasL) on tumor endothelial barrier selectively eliminates effector CD8+ T cells rather than Treg, due to the high expression of cellular FLICE-inhibitory protein (c-FLIP) expression on Treg." (PMID 30925919, 2019). "Upregulation of Fas ligand on intratumoral blood vessels through VEGF-mediated proangiogenic signaling by the tumor is another mechanism that reduces immune cell trafficking into the tumor microenvironment." (PMID 35582566, 2019). "EVs promote suppressive immunity by activating Fas ligand (FasL), to induce CD8+ T cell apoptosis and the polarization of THP-1 to tumor-associated macrophages (TAMs) of the M2 phenotype." (PMID 31681613, 2019). "The cytotoxicity is attributed to neutrophil-secreted H2O2 that induces influx of Ca2+ in cancer cells leading to apoptosis or to neutrophil Fas ligand-cancer cell Fas receptor interactions, which stalls tumor cell cycle progression from G1 to S phase." (PMID 30974896, 2019). "For example, tumour cells metastasising to the brain have to avoid apoptosis mediated by astrocyte-secreted Fas ligand and detection and elimination by reactive microglia." (PMID 30642388, 2019). "While these studies suggest tumor cell exosomes can indirectly affect T cell function, tumor exosomes containing Fas ligand can also directly induce CD8+ T-cell apoptosis." (PMID 30925917, 2019). "In cancer cells, over-expression of FASLG has been associated with increased risk of cancer progression while that of CD40L has been associated with proliferation and tumor progression, thereby promoting resistance by strengthening immunity." (PMID 31269724, 2019). "In the mechanisms limiting the infiltration of T cells into the tumor, a relevant role is also carried out by Fas Ligand (FasL) as a mediator of T cell apoptosis." (PMID 31370258, 2019). "CD8+ eliminate the tumor cells by inducing their apoptosis through the secretion of cytokines such as Fas-Ligand (FasL)." (PMID 31157216, 2019). "Peripheral and tumor-associated NK cells from STAT3-targeted tumor-bearing mice expressed elevated levels of NK activation markers NKG2D, CD69, Fas ligand (FasL) granzyme B, perforin, and IFNγ, resulting in reduced tumor growth and enhanced survival." (PMID 31057536, 2019). "PEITC reduced the growth of blood tumor cell by inducing Fas and Fas ligand (FasL) expression and ROS generation." (PMID 30445746, 2018). "Cytotoxic CD8+ TILs are major player in the immune response against tumour growth and their recognition of tumour-specific antigens allows killing of malignant cells through Fas ligand or perforin/granzyme pathways." (PMID 31225487, 2018).